BRAF (B-Raf proto-oncogene, serine/threonine kinase)
Diseases named in the same sentence as BRAF in open-access papers (continued):
Sharing a sentence is not in itself a finding about the gene and the disease.
adrenal tumor (1 paper, 2025). "Genetic mutations are common in PMEC, and in this case, molecular typing of the lung tumor tissue, adrenal tumor tissue, and plasma samples all revealed the presence of BRAF p.V600E, AKT1, and NFE2L2 mutations." (PMID 40896440, 2025). "In this case, NGS of the lung tumor tissue, adrenal tumor tissue, and plasma revealed positive BRAF p.V600E, AKT1, and NFE2L2 mutations, which are common genetic mutations." (PMID 40896440, 2025).
allergies (1 paper, 2025). "However, we can raise concerns about the possible development of hematologic irAEs in patients: 1) those with concomitant hematologic disease, 2) those with a history of multiple allergies, 3) those who previously experienced diarrhea as an irAE, and 4) those with N-RAS or uncommon BRAF mutations." (PMID 41567626, 2025).
androgenetic alopecia (1 paper, 2022). "SM in areas with androgenetic alopecia and elastosis occurs more frequently in elderly patients with chronic sun damage, presenting as the LM subtype, and without BRAF V600E mutation than SM without androgenetic alopecia and elastosis." (PMID 36064728, 2022). "BRAF V600E mutations occurred only in the absence of androgenetic alopecia (p = 0.048) and elastosis (p = 0.009)." (PMID 36064728, 2022). "BRAF V600K occurred at a similar frequency regardless of the presence of androgenetic alopecia (p = 0.697) or elastosis (p = 0.999)." (PMID 36064728, 2022).
ankylosing spondylitis (1 paper, 2010). An autoimmune chronic inflammatory disorder characterized by inflammation in the vertebral joints of the spine and sacroiliac joints. "Indeed, 35% of RA patients' sera contain autoantibodies to BRAF's catalytic domain versus 4% of ankylosing spondylitis patients' and 6% of healthy individuals'." (PMID 20955560, 2010).
apocrine carcinomas (1 paper, 2025).
arginine vasopressin deficiency (1 paper, 2025). "In conclusion, arginine vasopressin deficiency is widely prevalent in ECD, which is associated with a younger age, a higher frequency of BRAF V600E pathogenic variants, anterior pituitary endocrine dysfunction, absent T1-posterior pituitary bright spots, and abnormal pituitary imaging." (PMID 40075671, 2025).
asthma (1 paper, 2024). "A 10-year-old boy with a background of chronic allergic rhinitis and asthma was diagnosed with intracranial juvenile pilocytic astrocytoma (JPA) with BRAF fusion." (PMID 39166180, 2024).
Atrophy (1 paper, 2016). Any weakening or degeneration, especially through lack of use. "Here, based on the cellular models of neuronal atrophy, we demonstrate that BRAF has a general protective role in neuronal atrophy caused by dynein malfunction or mitochondrial impairment." (PMID 27510948, 2016). "Moreover, since both dynein and mitochondria are therapeutic targets in neurodegeneration, we are also wondering whether BRAF can protect against dendritic atrophy induced by mitochondrial dysfunction." (PMID 27510948, 2016).
autoimmune hepatitis (1 paper, 2025). Hepatitis caused by autoantibodies. "Seronegative Autoimmune hepatitis was confirmed by liver biopsy in one patient with a BRAF mutation." (PMID 40692796, 2025).
Bellini duct carcinoma (1 paper, 2021). "In this setting the dual BRAF and MEK inhibition resulted in improved progression-free survival and quality of life; Case 2: The second case shows aBRAF G466A mutated Bellini duct carcinoma (BDC), treated with dabrafenib and trametinib in second line therapy." (PMID 33669326, 2021).
benign brainstem tumors (1 paper, 2023). "For benign brainstem tumors, the identification of BRAF alterations permits to use new anti –BRAF drugs such as dabrafenid or vemurafenid or anti—MEK as trametinib or selumetinib." (PMID 37936887, 2023).
benign pituitary tumour (1 paper, 2021). "A few studies have identified the somatic mutation BRAF p.V600E as a driver of the non-secreting benign pituitary tumour, papillary craniopharyngioma." (PMID 33795686, 2021).
benign renal tumor (1 paper, 2018). "It should be noticed that metanephric stromal tumors (MST), another benign renal tumor, and the BRAF V600E mutation were frequently detected." (PMID 30111351, 2018). "Thus, novel genetic analysis, including BRAF V600E mutation in MA, could improve the diagnosis of this benign renal tumor." (PMID 30111351, 2018). "As MA is a rare, benign renal tumor, the clinical significance of this novel BRAF gene fusion remains unknown." (PMID 30111351, 2018).
bile duct adenoma (1 paper, 2024). A benign, well-demarcated polypoid neoplasm arising from the bile duct epithelium. "The presence of a high frequency of BRAF V600E mutations in bile duct adenomas suggests that they are true neoplasms and that they may be important precursors for the subset of ICCA that harbor BRAF mutations." (PMID 38672619, 2024).
bipolar disorder (1 paper, 2025). A disorder of the brain that causes unusual shifts in mood, energy, activity levels and the ability to carry out day-to-day tasks. "Moreover, reduced levels of BRAF have been found in bipolar disorder brains." (PMID 39645539, 2025).
bleeding disorders (1 paper, 2021). "The mutational spectrum of patients with bleeding disorders was largely overlapping with that of the NS general population, including mutations in PTPN11, SOS1, RIT1, BRAF, and MAP2K1 genes." (PMID 34857025, 2021).
blepharitis (1 paper, 2024). Inflammation of the eyelids near the eyelashes. "The most common ocular surface adverse effects are DED, conjunctivitis, and corneal damage, while blepharitis and meibomian gland dysfunction appear to be related to only a few of these new drugs, such as immune checkpoint inhibitors, BRAF inhibitors, aromatase inhibitors, and proteasome inhibitors." (PMID 38254833, 2024).
bone sarcoma (1 paper, 2023). A sarcoma that arises from the bone. "Furthermore, we discovered two GAs in the ALK and BRAF genes that occurred in bone sarcomas, while three GAs in the EGFR gene and one GA in the ERBB2 gene were only found in STS." (PMID 37546405, 2023).
Brain atrophy (1 paper, 2019). Partial or complete wasting (loss) of brain tissue that was once present. "Furthermore, two other BRAF V600E positive CNS-JXG cases in our series also had features suggestive of ECD with progressive multifocal CNS disease resulting in cognitive decline, including brain atrophy." (PMID 31685033, 2019).
brainstem tumors (1 paper, 2023). "For brainstem tumors, two main oncogenic pathways have been individualized: the BRAF pathway that is usually associated with benign tumors and the histone pathway that characterizes malignant neoplasms." (PMID 37936887, 2023).
bronchiogenic carcinoma (1 paper, 2021). "The lung recipient was a 49-yr-old male who developed a BRAF V600E–positive bronchiogenic carcinoma after transplantation and died." (PMID 34301805, 2021).
celiac disease (1 paper, 2025). An autoimmune genetic disorder with an unknown pattern of inheritance that primarily affects the digestive tract. "Other reported manifestations included psoriasis and celiac disease, each identified in two individuals (3.6%; one with a BRAF and one with a MAP2K1 mutations, respectively)." (PMID 40692796, 2025).
central hypogonadism (1 paper, 2025). "Multivariate analysis adjusting for age, BMI, and sex demonstrated that younger age, male sex, BRAF V600E pathogenic variants, central hypogonadism, and primary hypothyroidism were independently associated with a higher odds of AVP-D." (PMID 40075671, 2025). "In models adjusting for age, sex, and BMI, the BRAF V600 E pathogenic variant [OR (95%CI) 7.38 (1.84 to 39.01)], central hypogonadism [OR (95%CI) 6.19 (1.44 to 34.80)], and primary hypothyroidism [OR (95%CI) 13.89 (1.40 to 406.5)] emerged as being associated with a higher odds of having AVP-D." (PMID 40075671, 2025).
Cerebellar hypoplasia (1 paper, 2022). Cerebellar hypoplasia is a descriptive term implying a cerebellum with a reduced volume, but a normal shape and is stable over time. "Recently, a large exome sequencing study of children and adults with DWM and cerebellar hypoplasia expanded the list of genes associated with DWM to include TUBA1A, BRAF, SETD2, FOXP1, PUS3, ARMC9, and PIBF1." (PMID 35202430, 2022).
chronic heart failure (1 paper, 2024). "With clinical improvement (regression of chronic heart failure clinic), the patient was discharged for outpatient treatment, and a paraffin block of pericardium was sent for the genetic study of mutation in the BRAF gene in order to exclude Erdheim–Chester disease." (PMID 39337571, 2024).
colorectal mucinous adenocarcinoma (1 paper, 2021). An invasive colorectal adenocarcinoma characterized by the presence of extracellular mucin pools that contain malignant glandular epithelial structures. "Colorectal mucinous adenocarcinoma is a subtype of CRC with prominent mucin production associated with advanced stage at diagnosis, and BRAF mutation." (PMID 33836681, 2021).
craniosynostosis (1 paper, 2024). Craniosynostosis is defined as the premature fusion of one or more cranial sutures leading to secondary distortion of skull shape resulting in skull deformities with a variable presentation. "Craniosynostosis has been described in individuals with pathogenic variants in other genes of the RAS/MAPK pathway including BRAF, KRAS, PPP1CB, SHOC2, PTPN11, RAF1, and HRAS." (PMID 37774117, 2024).
cutaneous melanocytic neoplasm (1 paper, 2021). "BAP1 is a tumor suppressor gene and individuals with cutaneous melanocytic neoplasm with a germline BAP1 mutation, often have BRAF mutations, with these lesions reported to have a benign clinical course." (PMID 34071371, 2021).
delirium (1 paper, 2022). A disorder characterized by confusion; inattentiveness; disorientation; illusions; hallucinations; agitation; and in some instances autonomic nervous system overactivity. "We here describe the first patient with psychiatric manifestations of delirium revealing ECD with neurological involvement with favorable evolution under interferon followed by BRAF inhibitor monotherapy." (PMID 35874752, 2022). "Treatment with interferon resulted in the resolution of delirium, and treatment with BRAF inhibitor subsequently resulted in a partial remission of all active sites." (PMID 35874752, 2022).
dementia (1 paper, 2024). Loss of intellectual abilities interfering with an individual's social and occupational functions. "In addition, a case report of a patient with BRAF-related CFC delineated dementia-like symptoms and progressive decline from the early 30 s, despite well-controlled complications including neonatal-onset epilepsy." (PMID 39086472, 2024).
dendritic cell neoplasms (1 paper, 2024). "Assessment of BRAF mutational status has been used to aid in the diagnosis and guide treatment of histiocytic/dendritic cell neoplasms." (PMID 39592527, 2024). "Distinction of BRAF V600E mutated histiocytic/dendritic cell neoplasms requires consideration of distinctive histopathological and immunophenotypic findings in appropriate clinical and radiologic setting." (PMID 39592527, 2024). "BRAF mutations have been reported in other histiocytic/dendritic cell neoplasms, but some may represent mixed histiocytosis." (PMID 39592527, 2024). "BRAF V600E mutations are present in tumors of histiocytic/dendritic cell origin with the highest frequency in LCH and ECD among histiocytic/dendritic cell neoplasms." (PMID 39592527, 2024).
dendritic cell sarcoma (1 paper, 2014). A sarcoma that involves the dendritic cell. "We also genotyped three follicular dendritic cell tumors that were wild-type, which has not been previously examined; however, a BRAF V600E mutant interdigitating dendritic cell sarcoma has been recently reported." (PMID 24938183, 2014).
dermatophytosis (1 paper, 2024). A common fungal infection of the stratum corneum of the skin, hair, or nails by a dermatophyte. "The predisposing factors include chronic untreated dermatophytosis, impaired skin barrier secondary to trauma, animal exposure, immunocompromised patients, long-term use of steroids, chemotherapeutic drugs, use of adalimumab in organ transplantation patients, and BRAF inhibitors (vemurafenib)." (PMID 39559684, 2024).
desmoplastic melanoma (1 paper, 2022). A melanoma of the skin characterized by a proliferation of atypical spindled melanocytes in the dermis, in a background of abundant collagen. "Not only did the histological features change with time but also the pattern of growth also changed from metastatic to locally infiltrative, although it still retained a BRAF mutation which is unusual in desmoplastic melanoma." (PMID 34286349, 2022).
diabetic foot ulcers (1 paper, 2021). "Collectively, these studies demonstrated that topically applied BRAF inhibitors may be used in impaired wounds, such as diabetic foot ulcers, to enhance skin wound healing through paradoxical BRAF activation." (PMID 34161353, 2021).
duodenal carcinoma (1 paper, 2023). "The second patient had duodenal carcinoma with pancreatic invasion, in which BRAF V600E was found to be a driver gene mutation in the WES and was immunohistochemically confirmed to have MLH1 and PMS2 deletions." (PMID 36999887, 2023).
Dyskinesia (1 paper, 2018). A movement disorder which consists of effects including diminished voluntary movements and the presence of involuntary movements. "Dabrafenib also activates ERK in cells with wild-type BRAF and thus may potentially exacerbate dyskinesia." (PMID 30137437, 2018).
Dyslipidemia (1 paper, 2022). "For the first time, we describe dyslipidemia as a possible side effect of the BRAF inhibitors." (PMID 35681673, 2022).
edema (1 paper, 2021). An abnormal accumulation of fluid beneath the skin, or in one or more cavities of the body. "Peripheral edema is a common adverse event and has been reported to occur in 28%–36% of cases of BRAF V600E‐mutant NSCLC,3, 21 but most patients experienced mild (grade 1 or 2) peripheral edema." (PMID 33215864, 2021).
end stage renal failure (1 paper, 2016). "This also shows clinical safety of Vemurafenib in end stage renal failure and highlights the need for closer look at the subgroup of patients with BRAF V600K mutation and its tumour biology." (PMID 26989536, 2016). "Previously, this case was reported regarding safety of Vemurafenib in end stage renal failure and the same case was followed-up for 36 months and showed a sustained complete response even after stopping the BRAF inhibitor treatment." (PMID 26989536, 2016).
endometrial adenocarcinoma (1 paper, 2017). "In endometrial adenocarcinoma, the BRAF V600E mutation has been rarely reported." (PMID 28078189, 2017).
endothelial dysfunction (1 paper, 2022). In vascular diseases, endothelial dysfunction is a systemic pathological state of the endothelium (the inner lining of blood vessels) and can be broadly defined as an imbalance between vasodilating and vasoconstricting substances produced by (or acting on) the endothelium. "In addition, tumor‐induced endothelial dysfunction was significantly reduced, suggesting the synergistic anticancer effect of the BRAF/PI3K inhibitor." (PMID 36026581, 2022).
enterovirus infection (1 paper, 2023). "More importantly, we showed the inhibitory effect of vemurafenib in A549 cells, which do not carry the mutated BRAFV600E, further suggesting that enterovirus infection is not halted due to the inhibition of BRAF, but some other mechanism." (PMID 37436162, 2023). "Since vemurafenib did not seem to inhibit enterovirus infection through BRAF, we wanted to study in detail, step by step, at what stage vemurafenib exerts its effect against enteroviruses." (PMID 37436162, 2023). "Furthermore, we showed that downstream signaling from BRAF to ERK was not affected by vemurafenib, as the enterovirus infection caused similar activation of ERK with or without vemurafenib treatment." (PMID 37436162, 2023).
eosinophilic esophagitis (1 paper, 2025). Eosinophilic esophagitis (EoE) is a chronic, allergic disease of the esophagus characterized clinically by symptoms of esophageal dysfunction (including vomiting, dysphagia, feeding disorders, food impaction and abdominal pain) which persist after treatment with proton pump inhibitors (PPIs). "Eosinophilic esophagitis and thyroid disease occurred in two individuals, both carrying BRAF mutations." (PMID 40692796, 2025).
epithelial colon tumor (1 paper, 2024). "Future studies should investigate the effect of activation of BRAF on fibroblast-epithelial colon tumor communications and the potential contribution of RevCSCs to poor outcomes in patients with BRAFV600E CRC." (PMID 38893159, 2024).
esophageal tumors (1 paper, 2024). "In the current study, with regards to non-CRC GI tumors, we also found that fusions were more frequent in pancreatic as well as esophageal tumors, accounting for 25% and 10% of BRAF alterations occurring in those tumor types, respectively." (PMID 38791902, 2024).
extracutaneous melanoma (1 paper, 2014). "Because mutations in c-KIT (and BRAF) are now being successfully exploited by new targeted therapies, it would appear appropriate to perform relevant mutation testing of primary extracutaneous melanoma in patients in whom systemic treatment is being considered." (PMID 24679002, 2014).
familial breast cancer (1 paper, 2014). "We discovered several well-established cancer mutations in single samples, including a BRAF V600E mutation (cell line A673), a PI3KCA mutation (cell line ES4) that has been recurrently found in multiple cancer types, and a RAD51 alteration (tumor EWS101) associated with familial breast cancer." (PMID 25010205, 2014).
familial melanoma (1 paper, 2011). Familial melanoma (FM) is a rare inherited form of melanoma characterized by development of histologically confirmed melanoma in two first degrees relatives or more relatives in an affected family. "A similar finding was previously reported in familial melanoma, with CDKN2A as well as BRAF and NRAS mutations." (PMID 22039425, 2011).
glomangiosarcoma (1 paper, 2024). "Here, we report the impressive clinical and morpho-metabolic response of a metastatic BRAF V600E-mutated glomangiosarcoma after treatment with encorafenib and binimetinib." (PMID 39392364, 2024).
granulomatosis with polyangiitis (1 paper, 2020). A small-vessel necrotizing vasculitis characterized by the association of inflammation of the vessel wall and peri- and extravascular granulomatosis. "Here, we discuss a case of a patient diagnosed with granulomatosis with polyangiitis (GPA) shortly after starting treatment with dabrafenib and trametinib for BRAF V600E positive metastatic lung adenocarcinoma." (PMID 32131760, 2020).
hereditary cancer syndrome (1 paper, 2021). "Such basket trials not only focus on the gate keeper-type oncogene mutations, such as HER2 and BRAF, but also focus on the caretaker-type tumour suppressor genes, such as BRCA1/2, mismatch repair-related genes, which cause hereditary cancer syndrome." (PMID 33562094, 2021).
hypertensive heart disease (1 paper, 2022). Abnormal enlargement of the heart resulting from long-standing hypertension. "On the other hand, BRAF inhibitors may be beneficial in, for example, hypertensive heart disease to reduce interstitial fibrosis." (PMID 36331065, 2022).
hypogammaglobulinemia (1 paper, 2025). "Genotype-phenotype analysis revealed that BRAF mutations were predominantly associated with T-cell lymphopenia, whereas MAP2K1 mutations were linked to monocytosis, reduced naïve and switched-memory B cells, and hypogammaglobulinemia." (PMID 40692796, 2025).